MTF2 (metal response element binding transcription factor 2)
Diseases named in the same sentence as MTF2 in open-access papers (continued):
Sharing a sentence is not in itself a finding about the gene and the disease.
cancer (9 papers, 2020 to 2025). A tumor composed of atypical neoplastic, often pleomorphic cells that invade other tissues. "We next analysed the mutational status of MTF2 to determine its potential as a driver mutation of various cancer types using cBioportal data." (PMID 37895228, 2023). "High expression of MTF2 was also found to be associated with the sensitivity of Zibotentan across cancer cell lines (P value = 5.93E-09)." (PMID 33281885, 2020). "Furthermore, MTF2 downregulation has been associated with advanced stages and poor outcomes in various cancers, indicating its role as a common tumour suppressor." (PMID 40156159, 2025). "Indeed, a high expression of MTF2 is linked to a poorer patient prognosis in this cancer type, and a depletion of MTF2 leads to reduced proliferation of cells in vitro and in xenograft experiments, supporting a putative oncogenic role of MTF2 in this context." (PMID 37107696, 2023). "Additional studies have implicated MTF2 in the progression of various cancers, for which it may also serve as a prognostic and therapeutic biomarker." (PMID 37895228, 2023). "Inducible expression and degradation systems such as auxin-inducible degron technology to regulate MTF2 expression in a host of cancer cell lines would be valuable tools to reveal the functions of MTF2 in a context-specific fashion." (PMID 37895228, 2023). "Consistent with the rarity of MTF2 mutations in AML, the incidence of MTF2 mutations is very low across cancer types, with a recorded mutation rate of 1.5% observed among 10,953 patients encompassing 32 different cancer types." (PMID 37895228, 2023). "Even with these limitations in mind, it is interesting to note that Kaplan–Meier analyses of all available GEPIA2 data revealed that cancers with low MTF2 mRNA levels trend towards poor overall survival rates." (PMID 37895228, 2023). "To begin, we first analysed the mRNA expression levels of MTF2 in various cancers using TCGA data from the GEPIA2 (Gene Expression Profiling Interactive Analysis) web server." (PMID 37895228, 2023). "Here, we will review published studies and present data mined from publicly available databases to consider a variety of potential context-specific roles of MTF2 in cancer." (PMID 37895228, 2023). "The cancer-related role of MTF2 appears rather versatile and can both promote and inhibit tumor growth." (PMID 37107696, 2023). "Cancer cell lines with high expression of MTF2 were more resistant to Refametinib (P value = 6.89E-10)." (PMID 33281885, 2020). "MTF2 expression is correlated with age and is differentially expressed in thirty cancers." (PMID 39480826, 2024). "Determining whether MTF2 function is modified by specific posttranslational modifications could provide critical insight into the divergent roles of MTF2 in cancer." (PMID 37895228, 2023). "Due to the lack of control tissues in the TCGA datasets, patients were categorised as “high MTF2” if the RNA-seq MTF2 reads were greater than the mean MTF2 reads of the cancer dataset versus “low MTF2”, in which the RNA-seq transcript levels were below the mean MTF2 expression." (PMID 37895228, 2023). "We sought to determine whether unbiased pathway analysis across cancers could provide insight into tumour suppressor versus oncogenic functions of MTF2." (PMID 37895228, 2023). "We advocate for studies to be performed in these cancers to determine whether MTF2 plays a role in disease pathogenesis or may be useful as a biomarker." (PMID 37895228, 2023). "Hence, mass spectrometry approaches designed to identify posttranslational modifications in MTF2 in various cancer cell lines should be considered." (PMID 37895228, 2023). "This analysis should identify cancers in which altered MTF2 expression is common." (PMID 37895228, 2023).
cancer (continued). "Together, these data point to differential MTF2 mRNA levels exerting effects on different underlying biological processes that may be fundamental to the various cancer types, tissues, and microenvironments and identifies PRKCD as a potential pathogenic target of MTF2 regulation." (PMID 37895228, 2023). "Furthermore, immunoprecipitation-based proteomics analyses could reveal tissue-specific co-factors that moderate the MTF2 function in cancer." (PMID 37895228, 2023). "Future research should focus on developing specific inhibitors of PCIF1, potentially in combination with epigenetic therapies aimed at restoring MTF2 function, to effectively manage OSCC and possibly other cancers influenced by similar regulatory mechanisms." (PMID 40156159, 2025). "In the following, we will address the known roles of PHF1, MTF2, and PHF19 in cancer and the possible mechanisms involved." (PMID 37107696, 2023). "In contrast to PHF1 and MTF2, PHF19 has primarily been described as an oncogene in multiple cancer types." (PMID 37107696, 2023). "A recent study reported that PRC2 complex containing MTF2 represses expression of NLRC5 and its target genes, including MHC‐I and antigen presentation machinery‐related genes, in cancer cells." (PMID 37452654, 2023). "Previously, EZH2, SUZ12, EED, MTF2 and JARID2 have all been suggested to not only act as oncogenes, but also to have tumor suppressor activities, depending on the type of cancer." (PMID 38562687, 2024). "Thus, although these data globally support a tumor-suppressive role of PHF1, an oncogenic role of PHF19, and a relatively neutral role of MTF2, the three PCL proteins appear to have individual impacts dependent on the cancer type." (PMID 37107696, 2023). "MTF2 expression is not strongly affected in most cancer types, and its expression does not correlate with patient survival." (PMID 37107696, 2023). "MTF2 is highly conserved, and as an accessory subunit of PRC2, it has important roles in embryonic stem cell self-renewal and differentiation, development, and cancer progression." (PMID 37895228, 2023). "Given that MTF2 restoration in our rescue experiments reversed the oncogenic effects of PCIF1 knockdown, targeting the PCIF1‐MTF2 axis could offer a promising therapeutic strategy, not only in OSCC but also in other cancers where this pathway is dysregulated." (PMID 40156159, 2025).
tumor (7 papers, 2020 to 2025). "In both cohorts, reduced MTF2 levels were associated with higher tumour grade, advanced stage, recurrence and poor treatment response." (PMID 40156159, 2025). "Mechanistically, immunohistochemical analysis demonstrated that PCIF1 knockout combined with anti‐PD1 treatment not only reduced the proliferation marker Ki67 but also led to a pronounced upregulation of the tumour suppressor MTF2." (PMID 40156159, 2025). "Functioning as a tumour suppressor, MTF2 mediates gene silencing through PRC2‐driven H3K27me3 trimethylation, effectively repressing oncogene transcription." (PMID 40156159, 2025). "Clinical analyses further reveal that high PCIF1 expression and low MTF2 expression correlate with advanced tumour stage, poor treatment response and decreased overall survival." (PMID 40156159, 2025). "Our data suggest that PCIF1‐mediated m6Am modifications directly inhibit MTF2 translation, creating a feedback loop that disrupts chromatin‐mediated gene repression, thereby promoting tumour progression." (PMID 40156159, 2025). "IHC analyses showed that PCIF1 deletion was associated with reduced expression of Ki67, a proliferation marker, whereas MTF2 deletion increased Ki67 expression, highlighting MTF2's tumour‐suppressive role." (PMID 40156159, 2025). "In contrast, MTF2 knockout led to increased tumour size, whereas the combined knockout of both PCIF1 and MTF2 further exacerbated tumour formation, demonstrating a compensatory oncogenic effect in the absence of MTF2." (PMID 40156159, 2025). "The expression of PCIF1 and MTF2 in tumour tissues was consistent with these findings: PCIF1 loss decreased PCIF1+ cell populations, whereas MTF2 loss increased MTF2+ cells." (PMID 40156159, 2025). "Our review of the literature and bioinformatic analyses of publicly available data refute this model, as MTF2 functions as a tumour suppressor or an oncogene, depending on the tissue context." (PMID 37895228, 2023). "This is consistent with mouse xenograft studies, which demonstrated that MTF2 overexpression significantly inhibits MCF-7 tumour growth in vivo." (PMID 37895228, 2023). "The emerging paradoxical evidence suggesting that MTF2 has divergent roles as either a tumour suppressor or an oncogene in different tissues merits further investigations." (PMID 37895228, 2023). "Hypermethylated promoter regions in ALK tumor cells showed strong enrichment of binding sites for proteins associated with chromatin remodeling in ESC, in particular PRC associated proteins including CBX7, EZH2, MTF2, PHF19, RING1B, RNF2, and SUZ12." (PMID 33310759, 2021). "Thus, most studies propose a more tumor-suppressive role of MTF2." (PMID 37107696, 2023). "Specifically, PCIF1 knockout in our mouse models significantly reduced tumour incidence, supporting the notion that inhibiting PCIF1 could offer therapeutic benefits by restoring MTF2 function." (PMID 40156159, 2025). "Mechanistic experiments that manipulate MTF2 expression are required to determine in which tissues MTF2 functions as a tumour suppressor, oncogene, or neither." (PMID 37895228, 2023).
MTF2 also shares sentences with these, for which no sentence is quoted: esophageal cancer (2 papers); multiple myeloma (2); acute coronary syndrome (1); adrenocortical carcinoma (1); gastric cancer (1); head and neck squamous cell carcinoma (1); heart failure (1); kidney Chromophobe (1); lung adenocarcinoma (1); lung squamous cell carcinoma (1); malignant glioma (1); ovarian carcinoma (1); ovarian serous cystadenocarcinoma (1); prostate adenocarcinoma (1); serous cystadenocarcinoma (1); Wilms tumor (1).